MTOR (mechanistic target of rapamycin kinase)
Diseases named in the same sentence as MTOR in open-access papers (continued):
Sharing a sentence is not in itself a finding about the gene and the disease.
cancer (continued). "On the contrary, the abnormal activation of mTOR and p70S6K kinases has been reported as dictating cancer development in various human tumors." (PMID 32111101, 2020). "Pharmacological induction of autophagy through mTOR inhibition has a therapeutic effect as well as potential for prevention of cancer." (PMID 33053749, 2020). "We next explore the HIF-related cancer hallmark pathways, including apoptosis, cell cycle, DNA damage response, EMT, hormone AR, hormone ER, PI3K/AKT, RAS/MAPK, RTK, and TSC/mTOR." (PMID 33299416, 2020). "Previous studies have found that the AKT/mTOR signaling pathway is one of the most important signaling pathways in cancer, and it plays an important role in cell proliferation and survival." (PMID 32685545, 2020). "Given the prominent role of mTOR in cancer drug resistance and the yet limited clinical success with mTOR inhibitors, we aimed to identify novel therapeutic options for cancer cells with mTOR-dependent drug resistance." (PMID 32943635, 2020). "The PI3K/Akt/mTOR and PTEN pathway, and its deregulation, was directly linked to cancer cell proliferation and cancer progression in many different cancers." (PMID 32883003, 2020). "Deregulation of the mTOR signaling pathway is one of the most commonly observed pathological alterations in human cancers." (PMID 33144562, 2020). "In the current studies, mTOR has emerged as a critical effector commonly deregulated in human cancer, especially in NSCLC." (PMID 32576196, 2020). "The activation of the phosphoinositide 3-kinase (PI3K)/v-akt murine lymphoma viral oncogene homolog (AKT)/mammalian target of rapamycin (mTOR) pathway is a main driver of cell growth, proliferation, survival, and chemoresistance of cancer cells." (PMID 32033478, 2020). "For example, genes within the PI3K-Akt-mTOR pathway were found commonly altered in each cancer type with more than 70% prevalence." (PMID 33194730, 2020). "Several reseaches illustrated that FBXW7 plays critical roles in cancers by regulating Notch and mTOR." (PMID 32239181, 2020). "Our results indicated that STAT3 regulates MLST8 gene expression and facilitates the formation of mTORC1/2, cooperating with the mTOR pathway in cancer cell proliferation." (PMID 32495998, 2020). "Our results showed that RHEB, a key regulator of mTOR signaling, exhibited a high expression level in cancer samples, compared with normal and adjacent normal samples." (PMID 32807131, 2020). "In cancer cells, protein synthesis relies on mTOR signaling, in which the activation of mTOR activity enhances S6K and then S6 protein expression to synthesize proteins." (PMID 32731591, 2020). "The phosphatidylinositol 3-kinase/AKT/mammalian target of the rapamycin (PI3K/AKT/mTOR) pathway is a key signaling driver of cellular proliferation and survival of cancer cells." (PMID 32795346, 2020). "The interactions between paclitaxel, PI3K/Akt/mTOR and miRNAs in BC provide significant insight on the pathology of disease which also open new venues for treating this cancer." (PMID 33292283, 2020). "The Akt/mammalian target of rapamycin (mTOR) signaling pathway is another pathway that is commonly deregulated in cancer." (PMID 32664703, 2020). "The mTOR/S6K signaling pathway is an important regulator of cell growth and it is related to tumorigenesis and cancer aggressiveness." (PMID 33133551, 2020). "Introduction: mTOR inhibitors are anticancer agents affecting mTOR/AKT/PI3K pathway that is one of the most important in human cancer cells." (PMID 33173419, 2020). "Our data demonstrate that PGRMC1 plays a prominent role in regulating the growth of cancer cells by altering the PI3K/AKT/mTOR and EGFR signalling mechanisms in both ER-positive and TNBC cells." (PMID 32704174, 2020). "The Akt/mTOR/p70 and ERK1/2 pathways are frequently associated with oncogenesis in a variety of cancer cell types, including malignant gliomas." (PMID 32765806, 2020).
cancer (continued). "The most common mTOR inhibitors are temsirolimus and everolimus used for different types of cancer such as HER2-negative breast cancer, pancreatic neuroendocrine tumors, estrogen-receptor-positive, and renal-cell carcinoma." (PMID 33552973, 2020). "The mammalian (mechanistic) target of rapamycin (mTOR) inhibitors everolimus, sirolimus, and temsirolimus are effective anti-cancer agents in neuroendocrine, breast and renal cell carcinomas." (PMID 33081013, 2020). "AKT/mTOR is an essential signaling pathway responsible for the modulation of cancer cell biological activities such as proliferation and migration." (PMID 31682716, 2020). "Proteins involved in cancer relevant signaling pathways including PI3K/Akt/mTOR, the cell cycle, and PDL1 were differentially abundant between subsites." (PMID 33396315, 2020). "The AKT/mTOR signaling pathway plays a key role in cancer stem cells (CSCs) maintenance and viability in BC25–28." (PMID 33311440, 2020). "JPH203 inhibits the function of the LAT1 in many types of cancer cells, which functions through the mTOR signaling pathway to block their migration/invasion activities and induce apoptosis." (PMID 31992742, 2020). "Background and objectives: Everolimus (EVE) is a mammalian target of the rapamycin (mTOR) inhibitor that is widely used in cancer patients." (PMID 32668776, 2020). "SNHGs also activate the signaling pathways commonly involved in cancer development and progression, such as Wnt/β-catenin and mTOR/PI3K/AKT." (PMID 32318335, 2020). "Phosphatidylinositol-3-kinase (PI3K)/AKT/ mammalian target of rapamycin (mTOR) signaling is the most commonly activated cancer driver pathway, leading to cell proliferation and survival." (PMID 32486021, 2020). "Rapamycin (Rapa), which is a specific inhibitor of the mammalian target of Rapa (mTOR), is known to possess anti-cancer effects." (PMID 32599712, 2020). "It has been reported that AKT is activated by phosphoinositide-dependent kinases 1 (PDK1), and then signal transduction occurs through downstream effectors such as mTOR to increase cancer cell proliferation." (PMID 33134174, 2020). "Cancer stem cell-like and metastatic cells rely on enhanced mTOR activity, and EVI1 maintains this signaling by transcriptional upregulation of key pathway components and metastatic mediators." (PMID 32012804, 2020). "Aberrant activation of mitogenic signaling pathways in cancer promotes growth and proliferation of cells by activating mTOR and S6 phosphorylation, and D-cyclin kinases and Rb phosphorylation, respectively." (PMID 32391118, 2020). "Sapanisertib (otherwise known as INK128 or MLN1028, 4) is an experimental kinase inhibitor, currently in clinical trials for several cancer indications. is an example of a mTOR inhibitor, inhibiting both the mTORC1 and 2 complexes." (PMID 33479617, 2020). "While some of them have been approved to treat human cancer, more mTOR inhibitors are being evaluated in clinical trials." (PMID 32070055, 2020). "For example, mTOR signaling is unaffected when cancer cells are shifted to homocysteine medium, and constitutively active mTOR cannot override the SAM-checkpoint-mediated cell cycle arrest." (PMID 32276408, 2020). "Inhibitors of PI3K/Akt/mTOR are being extensively investigated for the ability to revert/prevent cancer development in preclinical and clinical settings." (PMID 32429547, 2020). "A commercial custom array panel of cancer research was used to evaluate the expression of several genes involved in cell cycle, apoptosis, DNA repair, cellular metabolism, and mTOR or MAPK/ERK pathways." (PMID 33339207, 2020). "The control of mTOR signaling is critical for the cells and its dysregulation leads to several diseases such as cancer, diabetes, and metabolic diseases." (PMID 33195279, 2020). "Stimulation of the PI3K/Akt/mTOR regulatory axis by the growth factors in cancer cells, augments many of the metabolic processes that support cell growth." (PMID 32318579, 2020).
cancer (continued). "Inhibition of the PI3K (phosphatidylinositol 3-kinase)/AKT/mTOR signaling pathway is employed in therapeutic approaches for certain cancer types." (PMID 32597485, 2020). "Activating mutations in PI3K, mTOR, and the Akt isoforms, and loss-of-function mutations and deletions in PTEN occur in about 27%, 8%, 3%, and 19% of all cancer cases, respectively." (PMID 32106627, 2020). "Short-lived populations from the outer margin of the species range have small population size and accumulate deleterious mutations in genes significantly enriched in the WNT signaling pathway, neurodegeneration, cancer and the mTOR pathway." (PMID 32869739, 2020). "We predict the most effective combination for OXPHOS cancer type as +GluT1 and -PKM2 and the one for glycolysis cancer type as +mTOR and +NOX, respectively." (PMID 32276228, 2020). "The signaling of mTOR (the target of rapamycin in mammalian cells) is unregulated in a wide range of human cancers." (PMID 32911759, 2020). "Loss of function of FBXW7 in several human cancers has clinical implications and prognostic value: the use of rapamycin has proven to inhibit breast cancer cells with loss of FBXW7 by mTOR inhibition." (PMID 32850962, 2020). "It has previously been demonstrated that PTEN functions as an inhibitor to AKT/mTOR pathway in many cancers." (PMID 32297644, 2020). "Relative high concentrations in L-leucine result in increased mammalian target of rapamycin (mTOR) activation, which supports growth and survival of cancer cells." (PMID 33066406, 2020). "The Akt (protein kinase B)/mammalian target of rapamycin (mTOR) pathway, which is dysregulated in various cancers, controls the assembly of eukaryotic translation initiation factor 4F (eIF4E) complex." (PMID 32023262, 2020). "Many studies have identified that the PI3K/AKT/mTOR pathway is critical in control cell cycle in cancer cells." (PMID 33659215, 2020). "The activation of the PI3K/AKT/mTOR pathway is a main driver of cell growth, proliferation, survival, and chemoresistance of cancer cells, and, for this reason, represents an attractive target for developing targeted anti-cancer drugs." (PMID 32033478, 2020). "The main KEGG processes mediated by PlncRNA-1 target genes were found to include multiple cancer surveillance pathways, focal adhesion, regulation of actin cytoskeleton, mTOR signaling pathway, Wnt signaling pathway, and transcriptional activity." (PMID 33288752, 2020). "Looking at each sub analysis, enrichment of miRNAs and mRNA fragments among the 88 significant RNAs in all TGCTs revealed several cancer related pathways, including mTOR, MAPK and ErbB2." (PMID 33251139, 2020). "Cinobufotalin injection blocks cancer cells in the G2/M phase, possibly by downregulating the expression of p-Akt, p-mTOR, and p-4E-BP, thus blocking the Akt/mTOR signaling pathway." (PMID 32148531, 2020). "The phosphoinositide 3-kinase (PI3K)-Akt-mammalian target of rapamycin (mTOR) pathway (PI3K-Akt-mTOR pathway) is among one of the intracellular pathways aberrantly upregulated in cancers including AML." (PMID 32326335, 2020). "mTOR is a target gene of miR-100-5p which binds to the 3′UTR directly and decreases the expression of mTOR and enhances chemo-sensitive of cancer cells." (PMID 32318350, 2020). "With the MAPK pathway closely linked with the PI3K/Akt pathway, a previous study showed the reduction of cancer cells growth through inhibiting the PI3K/Akt/mTOR signalling pathway." (PMID 33023525, 2020). "Some important studies have revealed interplays between miRNAs and mTOR pathway during cancer development." (PMID 33238430, 2020). "We found that cancer cells avoid autophagic cell death by mTOR activation through nutrient replenishment, such as with amino acids, which can be stalled by ATP depletion via blocking of OxPhos." (PMID 32883024, 2020).
cancer (continued). "Studies also report that PI3K/Akt/mTOR is activated, in particular in 30%–50% of PC, mainly due to the amplification of gene encoding components, advocating that targeted inhibition of those individual components of the signaling cascade might be a solid strategy for cancer therapy." (PMID 33258012, 2020). "Autophagy induction by mTOR inhibition or AMPK activation has been reported to have a therapeutic effect in cancer." (PMID 32260198, 2020). "The CCND1 involved in cell cycle progression; TEAD4, a transcription factor in the Hippo signaling pathway; and EIF4EBP1, the translational regulator in PI3K/Akt/mTOR signaling, have been found to be significantly deregulated in several cancers." (PMID 32908901, 2020). "Both in vitro cell culture and immunohistochemical studies of tumor tissue suggest drug induction of tumor cell apoptosis and inhibition of PI3k/mTOR pathways as well as cancer stemness." (PMID 33013390, 2020). "The AKT/mTOR signaling pathway has vital roles in cancer evolution, and its activation has been found in most BCs." (PMID 33293473, 2020). "The metabolism of drug-resistant cells is regulated by the PI3K/AKT/mTOR pathway which ultimately confer cancer cells drug resistance phenotype." (PMID 32038983, 2020). "The mechanisms of CIP2A activation and overexpression in cancer cells have been investigated by several studies, in which some pathways were found to be associated with development of cancer, such as PI3K/mTOR and MAPK/ERK signaling pathway." (PMID 32321509, 2020). "Although this activity has yet to be proven in humans, the localization signal is conserved in human GlyRS, and mTOR activation through GlyRS would be a beneficial pathway for cancer to exploit." (PMID 33266490, 2020). "The PI3K/Akt/mTOR signaling is a frequently hyperactivated pathway in cancer and is critical for the growth and survival of tumor cells." (PMID 32922544, 2020). "PTEN targeting by microRNAs result in mTOR pathway activation and dysregulation of these microRNAs lead to an uncontrolled cell proliferation leading to cancer." (PMID 33614488, 2020). "In Conclusion, PL with different concentrations can play the role of anti-cancer cells by regulating the expression of downstream effectors in the PI3K/AKT/mTOR pathway." (PMID 33117085, 2020). "One of the downstream pathways is the phosphoinositide 3-kinase (PI3K)/AKT/mammalian target of rapamycin (mTOR) pathway, known to be one of the most commonly activated signaling pathways in cancer, leading to cell proliferation, survival and differentiation." (PMID 32117774, 2020). "The constitutively active PI3K/Akt/mTOR signaling network is pivotal for tumor cell proliferation and survival in a variety of cancers including GBM." (PMID 33013390, 2020). "mTOR is a master regulator of cell growth and metabolism and is often dysregulated in a variety of cancers." (PMID 32226926, 2020). "The PI3K/Akt/mTOR pathway is commonly activated in human cancers and contributes to oncogenic transformation including proliferation, survival, and metabolic reprogramming." (PMID 32831114, 2020). "Phosphoinositide 3-kinase (PI3K) is a family of p85/p110 heterodimeric lipid kinases that regulates cancer cell proliferation, growth, motility, and survival via the activation of mammalian target of rapamycin (mTOR)." (PMID 32708855, 2020). "This Hippo-pathway effector protein led to the inhibition of cancer cell autophagy-related cell death through the intermediary signaling of the RAC1/ROS/ (mammalian target of rapamycin) mTOR pathway." (PMID 32545340, 2020). "As one type of mTOR inhibitors, rapamycin exerted effects on cancer growth and survival in vitro and showed a promising suppression on tumor growth in vivo." (PMID 32116708, 2020). "In one study, which validated the crosstalk between MAPK and PI3K/mTOR pathways using twenty-nine cancer cell lines from different origin, synergistic interaction between pathways were shown in cell lines with PTEN loss." (PMID 33182509, 2020).
cancer (continued). "The downregulation of mTOR pathway signaling reduces cancer growth and has therapeutic potential for CCA." (PMID 32318579, 2020). "Despite numerous conflicting reports concerning the biological function of RNF126 in cancer, our results indicate that RNF126 is associated with NTS-induced antileukemia effects via mTOR downregulation." (PMID 32131492, 2020). "AKT lies downstream of PI3K and is a key molecule in the PI3K/PTEN/AKT/mTOR signaling pathway that is frequently dysregulated in various cancers, including HCC." (PMID 32018226, 2020). "The PI3K/Akt/mTOR pathway represents an excellent sample of pathway redundancy in biological systems, especially in cancer cells." (PMID 32463592, 2020). "Metformin exhibits the ability to inhibit the multi drug resistance 1 (MDR1), thus re-sensitizing the cancer cells through the AMPK/mTOR pathway." (PMID 32872293, 2020). "The phosphoinositide 3‐kinase (PI3K)/AKT/mTOR pathway is frequently activated in various human cancers and has been considered a promising therapeutic target." (PMID 31725956, 2020). "Several mTOR inhibitors, including everolimus and temsirolimus, are under early Phase (I/II) clinical trials as a radiosensitizer to treat several cancer types such as prostate cancer, GBM, and lung cancer." (PMID 32983997, 2020). "Hyperphosphorylation of PRAS40, resulting in dissociation from mTORC1 and enhanced mTOR activation, has been found in a variety of cancers, including melanoma, prostate cancer, stomach cancer, and non‐small‐cell lung cancer." (PMID 32495998, 2020). "The Notch and mTOR signaling pathway are involved in the carcinogenesis of numerous cancers, and blockade of Notch and mTOR pathway appears to influence cell proliferation in various types of cancers." (PMID 32239181, 2020). "Although several mTOR inhibitors are available for cancer therapy, clinical trials using mTOR inhibitors have showed disappointing responses in PCa." (PMID 32645691, 2020). "PI3K/AKT/mTOR pathway is an intracellular signaling pathway significant for cell cycle and metabolism involved in cancer progression." (PMID 33489906, 2020). "Downstream of EGFR are PI3K-Akt (Akt) and mitogen-activated protein kinases (MAPK) which activate mammalian target of rapamycin (mTOR) and proto-oncogene c-Myc (c-Myc) that are often hyper-activated in cancers." (PMID 32328462, 2020). "There is abundant evidence in the current scientific literature which supports the notion that pharmacological inhibition of the PI3K/AKT/mTOR pathway components can radiosensitise cancer." (PMID 32443649, 2020). "The mTOR pathway is often disrupted in cancers, and the intersection between mTOR and TPCs suggests intriguing therapeutic possibilities." (PMID 33542897, 2020). "Temsirolimus, a specific inhibitor of mTOR, can regulate cell growth, proliferation, and survival in cancer cells." (PMID 32630642, 2020). "Its overexpression is associated with the hyperactivation of pathways, such as MAPK, JAK/STAT, RAS/MEK/ERK and PI3K/AKT/mTOR pathways, involved in cellular proliferation and differentiation of different cancers." (PMID 33105796, 2020). "This concept can be elaborated with examples of phosphatase and tensin homolog (PTEN) in PI3K (phosphatidylinositol 3-kinase)/Akt (protein kinase B) and mTOR (mammalian target of rapamycin) signaling in cancer cells." (PMID 32276464, 2020). "Taken together, these results indicated that m6A plays a fundamental role in the regulation cancer pathway such as the PI3K/Akt/mTOR pathway." (PMID 32863943, 2020). "It has been shown that PI3K/AKT/mTOR signaling pathway is important in controlling proliferation and apoptosis of various cancer cells." (PMID 32913452, 2020). "As a crucial mechanism involved in cellular physiological processes and tumor progression, the Akt/mTOR signaling pathway represents a hotspot in the treatment strategy of cancer." (PMID 32337219, 2020).